Y_RNA (Y RNA )
Gene: Miscellaneous RNA gene on chromosome 12 (54,099,191 to 54,099,302, reverse strand). Ensembl gene ENSG00000202146.
Homologues: Orthologues: chimpanzee Y_RNA (96% identical), macaque Y_RNA (88% identical). Paralogues in human: Y_RNA (96% identical), Y_RNA (95% identical), Y_RNA (94% identical), Y_RNA (93% identical), Y_RNA (92% identical), Y_RNA (87% identical), RNY1P5 (86% identical), Y_RNA (84% identical), Y_RNA (83% identical), Y_RNA (82% identical), Y_RNA (81% identical), RNY1 (80% identical), and 99 more.